CD36 (CD36 molecule (CD36 blood group))
Diseases named in the same sentence as CD36 in open-access papers (continued):
Sharing a sentence is not in itself a finding about the gene and the disease.
Obesity (continued). "Mechanistically, the regulated effect of adipocyte OGT on monocyte development may be mediated by NEFA-cluster of differentiation 36/fatty acid binding protein 4 (CD36/FABP4) pathway in HSCs in HFD-induced obesity." (PMID 40389445, 2025). "Based on these findings, we hypothesize that CD36 may serve as a pivotal factor in exacerbating ferroptosis in obesity-related SAP." (PMID 40331957, 2025). "Our findings show that spatially distinct adipose depots, specifically the abdominal SAT and mesenteric VAT, differentially affect endothelial Kir2.1 in vitro in obesity and provide new insight into the potential role of CD36 in mediating Kir2.1 and endothelial dysfunction." (PMID 38586877, 2024). "Taken together, these findings suggest that VAT may augment CD36 function and/or trafficking to the membrane to promote Kir2.1 impairment in obesity." (PMID 38586877, 2024). "Here we used a well-established mouse model of diet-induced obesity that we recently showed recapitulates the obese human condition in regard to VAT versus SAT endothelial function to determine the role of CD36 in mediating obesity-induced endothelial and Kir2.1 dysfunction in VAT arteries." (PMID 38586877, 2024). "BPA increases the number of adipocytes by regulating the expression of the FABP4, CD36, and PCSK1 genes; decreases the release of adiponectin and other adipokines; and disrupts adipocyte metabolism, thus increasing the risk of developing obesity." (PMID 39519574, 2024). "It should be noted that vitamin D protects against NAFLD, ameliorating hepatic steatosis owing to obesity-induced dyslipidemia, by reducing plasma lipid uptake through fatty acid translocase (FAT/CD36) and increasing hepatic mitochondrial β-oxidation via the PPARα signaling pathway." (PMID 39404394, 2024). "The importance of CD36 in obesity-induced endothelial dysfunction of VAT arteries was further supported in ex vivo pressure myography studies where CD36 ablation rescued the endothelium-dependent response to flow via restoring Kir2.1 and endothelial nitric oxide synthase function." (PMID 38586877, 2024). "Therefore, in this study, we use a well-established mouse model of diet-induced obesity to determine the role of VAT in mediating endothelial Kir2.1 dysfunction via CD36 by exposing endothelial cells to VAT and SAT from lean and obese mice in vitro." (PMID 38586877, 2024). "However, the excessive proliferation in Desulfobacterota would promote the expression of receptor CD36, which is involved in lipid absorption, thereby regulating the lipid absorption capacity of the host and affecting obesity." (PMID 37446612, 2023). "There is also no consensus regarding the role of CD36 polymorphisms and fat taste in the context of obesity." (PMID 36409650, 2023). "In addition, it is significantly increased in vascular lesions and the kidneys of patients with hyperglycemia and/or hyperlipidemia, suggesting the dysregulation of CD36 levels in obesity and related metabolic dysfunction." (PMID 37709134, 2023). "In general, obesity translated into a greater content of fatty acid transporters (especially CD36/SR-B2 and SLC27A4/FATP4) and boosted accumulation of all the examined lipid fractions, i.e., triacylglycerols (TAGs), diacylglycerols (DAGs), and free fatty acids (FFAs)." (PMID 37602323, 2023). "Furthermore, the CD36 gene in humans is currently being investigated as a potential target in some diseases, such as cardiovascular disease, metabolic syndrome, obesity, and cancer." (PMID 36816031, 2023). "All of these effects may contribute to the reduction in obesity-induced inflammation mediated by CD36 peptide treatment." (PMID 37980376, 2023). "Two studies explored the relationship between CD36 expression with fat taste in obesity." (PMID 36409650, 2023). "The weak correlation with obesity markers and the correlation with hepatic CD36 mRNA expression suggested that hepatic CD36 might contribute to the sCD36 circulation pool." (PMID 40625574, 2023).
Obesity (continued). "The results for this study suggest that CD36 peptide, as a TSP1 antagonist, may serve as a new therapeutic option for obesity-associated comorbidities." (PMID 37980376, 2023). "Similarly, obesity also increased the total CD36/SR-B2 protein content in subADMSCs-derived adipocytes (∼67% of data variability, p < 0.05) and in the mature fat cells of visADMSCs ancestry (25% of data variability, p < 0.05)." (PMID 37602323, 2023). "Adipogenesis is promoted by adipogenesis regulators such as peroxisome proliferator-activated receptor (PPARγ), CCAAT/enhancer binding proteins (C/EBPα), fatty acid synthase (FAS), and CD36, and abnormal regulation of adipogenesis contributes to obesity due to adipocyte dysfunction." (PMID 36838843, 2023). "Furthermore, the A. muciniphila monocolonized mouse model and its metabolomic analysis revealed that A. muciniphila exhibits an anti-obesity effect by downregulating Cd36 expression in the small intestine and inhibiting fatty acid absorption." (PMID 37709134, 2023). "Nonsense mutations in CD36 are also being associated with insulin resistance, familial type 2 diabetes, CD36-mediated ER stress and inflammatory signaling (JNK, NF-κB) implicated in diet-induced obesity and reduced insulin sensitivity." (PMID 36410795, 2023). "Furthermore, CD36 peptide treatment improved glucose tolerance and insulin sensitivity, and mitigated obesity-related fatty liver disease and kidney damage." (PMID 37980376, 2023). "Importantly, obesity, insulin resistance, and type 2 diabetes have been associated with increased FFA muscle plasma membrane transport and elevated CD36 levels." (PMID 36982383, 2023). "Lingual application of CD36 siRNA decreased fat preference in lean, obesity-resistant rats." (PMID 36409650, 2023). "The relationship between fat taste, CD36, and obesity has also been studied in humans." (PMID 36409650, 2023). "The high expression of CD36, TLR4, and NF-κB p65 in monocytes may be involved in chronic inflammation caused by obesity." (PMID 37403139, 2023). "The finding of the present study indicated that platelet CD36 may be the critical mediator between obesity and the prothrombotic phenotype in patients with NVAF." (PMID 36465448, 2022). "The expression of CD36 has been proven to be positively correlated with obesity in dairy cows." (PMID 36611624, 2022). "Hepatic CD36 expression is upregulated in patients with obesity and NAFL." (PMID 35700043, 2022). "Further investigations are needed to explore whether CILP2 can affect lipid metabolism through CD36 in adipose tissue, skeletal muscle, and other tissues under obesity." (PMID 35757483, 2022). "Overall, we demonstrated that CD36 was involved in skeletal muscle cell proliferation by cell cycle control, and these findings might facilitate the treatment of obesity-related muscle wasting." (PMID 36111143, 2022). "We hypothesize that the genetic and epigenetic changes at the CD36 gene locus could influence the onset of obesity and type 2 diabetes in these women." (PMID 35982478, 2022). "Furthermore, oxidative stress and a prothrombotic phenotype perturb FAT/CD36 function and induce metabolic diseases as obesity, insulin resistance, diabetes, atherothrombotic disease, chronic kidney disease, neurodegenerative disorders and multiple sclerosis." (PMID 36615118, 2022). "Similarly, obesity triggered increased expression of the liver-specific fatty acid transporter Fabp1 in hepatic cap ECs and of fatty acid transporters Fabp4, Cd36, Fabp5, Dbi and Lpl in art and ven ECs from AT." (PMID 36400935, 2022). "Studies in mice have found that CD36/FAT protein promotes the intestinal absorption of fatty acids, and the upregulation of cd36/fat expression in the liver is associated with hepatic TG accumulation, elevated serum TG, and obesity." (PMID 36295806, 2022). "Nevertheless, based on the evidence described in obesity, we speculate that CD36 expression and function could also be compromised in GD adipocytes and hepatocytes." (PMID 34957117, 2021).
Obesity (continued). "Independent of its physiological function, it is obvious that CD36 may participate in abnormal FA utilization and its deleterious consequences during insulin resistance and obesity (reviewed in Refs." (PMID 34360006, 2021). "Under this scenario, we suggest that LPA may also promote the expression of CD36 in NPC hepatocytes through the PPAR-γ pathway (similar to what was discussed in obesity), promoting lysosome dysfunction." (PMID 34957117, 2021). "Indeed, in obesity, lipid accumulation and lysosomal dysfunction in adipocytes and hepatocytes depends on the expression and role of CD36." (PMID 34957117, 2021). "An antibody to CD36 reversed the dysfunctional GSIS associated with CD36 overexpression, indicating that CD36 is a candidate therapeutic target for restoring SNARE protein levels and GSIS during obesity-associated T2D." (PMID 33673206, 2021). "In obesity, we speculate that B cells could also display elevated expression levels of CD36, which could regulate autophagy during their activation." (PMID 34957117, 2021). "While global CD36 deficiency was protective against high-fat diet-induced obesity and insulin resistance, absence of CD36 in macrophages (using a bone marrow transplant approach) was not, in spite of reduction in macrophage inflammatory pathways." (PMID 34888367, 2021). "Furthermore, a rise in CD36 levels contributes to the advancement of obesity-related metabolic dysfunctions by increasing lipid accumulation and inflammation." (PMID 34360006, 2021). "Whether CD36 gene methylation also controls other factors like PPAR- involved in obesity remains unanswered, but if yes, what does it control and how is it regulated?" (PMID 32585828, 2020). "Thus, our nanoString screen suggests that in renal tumors from subjects with obesity, increases in CD36 and IDO1, with concomitant decreases in T cell-related CD7 and CCL21, are consistent with a host environment that favors tumor progression." (PMID 32469992, 2020). "Since both obesity and type 2 diabetes have major comorbidities that make it imperative to understand the underlying mechanisms that control food intake and regulate energy and glucose homeostasis, the role of CD36 was further assessed in a rodent model of human obesity." (PMID 31474875, 2019). "CD36 binds long-chain fatty acids and facilitates their transport into cells, contributing to the pathogenesis of metabolic disorders such as diabetes and obesity." (PMID 31394746, 2019). "In fact, CD36 has been associated with obesity and diabetes in human diseases; Particularly, increased expression of hepatic CD36 is closely related to the development of NAFLD and non-alcoholic steatohepatitis (NASH) with insulin resistance." (PMID 30016988, 2018). "Here we showed that nicotine and obesity additively upregulated macrophage CD36 expression." (PMID 29236702, 2017). "Moreover, CD36 has been related with the inflammatory response present in obesity and metabolic syndrome." (PMID 28729885, 2017). "Since LPA directly promotes BC progression, it is tempting to further study whether these cells are TICs and whether obesity-derived LPA drives CD36 expression in a specific subpopulation of cells and render them become metastatic TICs." (PMID 28186980, 2017). "Furthermore, expression of CD36 on monocytes is increased in obesity, and a large body of evidence suggests that polarization of monocytes is mediated by CD36." (PMID 28168203, 2017). "CD36 mediates the uptake of FFAs across the cell membrane, and its high expression is usually associated with IR and type 2 diabetes, including HFD-induced obesity." (PMID 29295591, 2017).
Obesity (continued). "There is a controversy on how genetic variations in CD36 influence obesity." (PMID 27127449, 2016). "Cluster differentiating 36 (CD36) protein is highly expressed in the heart and regulates lipid utilization but its role in obesity-associated oxidative stress is still not clear." (PMID 27195707, 2016). "In the review, they stated that genetic variations of CD36 were not strongly associated with obesity." (PMID 27127449, 2016). "In order to evaluate whether obesity affected monocytes functions we evaluated the expression of CD36, TRL-2, TRL-4 and HLA-DR, CD40, CD80/86 molecules in NW and CO." (PMID 27977792, 2016). "Besides, a comparative study with cardiospecific CD36 overexpression is required to elucidate the specific effect of CD36 in obesity cardiomyopathy." (PMID 26036798, 2015). "Furthermore, CD36 mRNA expression levels are greatly enhanced in liver and adipose tissue of ob/ob mice, a monogenic model of obesity." (PMID 25866768, 2015). "We hypothesized that cardiospecific suppression of CD36, the predominant membrane FA transporter, would protect against obesity-related cardiomyopathy." (PMID 26036798, 2015). "Inhibition of cardiac CD36 may serve as a potential approach for treatment of obesity cardiomyopathy." (PMID 26036798, 2015). "Furthermore, mRNA levels of MSR1, CD36, and LOX-1 in whole adipose tissue specimens have been associated with obesity and insulin resistance in humans." (PMID 25224267, 2014). "Our results provide the first evidence that obesity may impair the orosensory detection of free LCFA via a mechanism in which the lingual CD36 plays a role in the mouse." (PMID 23840049, 2013). "We postulate that obesity might impair this signaling machinery by limiting the CD36 amounts in lipid rafts, which might restrain the subsequent signaling cascade and CD36 degradation." (PMID 23840049, 2013). "To determine whether the protection against HFD-induced obesity paralleled a reduction in AT inflammation, we evaluated the inflammatory status of adipose tissue in high-fat fed WT and CD36 KO mice." (PMID 22615812, 2012). "Increased hepatic CD36 activity is critical for the development of steatosis in obesity." (PMID 22723881, 2012). "Our studies confirmed earlier reports showing that mice lacking CD36 were significantly protected against HFD-induced obesity associated with increased plasma insulin and glucose levels and reduced glucose tolerance." (PMID 22615812, 2012). "However, to date, there have been limited studies linking CD36 to obesity-related SAP." (PMID 40331957, 2025). "CD36-deficient humans are not protected from hyperlipidaemia, have high circulating fatty acids and chylomicron remnants and are at increased risk of the metabolic syndrome and obesity complications." (PMID 39503770, 2025). "These previous experiments were conducted in vitro, and whether differences in systemic FA availability among adults with obesity may contribute to modifications in CD36 recruitment of Fyn to IRβ and modify IRβ phosphorylation and downstream insulin action in human skeletal muscle is not known." (PMID 39487600, 2025). "Furthermore, CD36 has been shown to be a key mediator of fatty acid uptake in skeletal muscle, and CD36 knockdown prevents diet-induced obesity, intramuscular lipid deposition, and oxidative stress, which results in impaired muscle satellite cell function and delayed muscle regeneration." (PMID 38032316, 2024). "In addition to vascular endothelium, CD36 is expressed in adipocytes and immune cells located in AT, each of which may play a role in inducing endothelial dysfunction in obesity." (PMID 38586877, 2024). "Moreover, the anti-obesity impact of IX is partially attributed to its ability to hinder fatty acid absorption, achieved by reducing the expression of the fatty acid transporter CD36 in the small intestine induced by A. muciniphila." (PMID 37709134, 2023).
Obesity (continued). "However, the in vivo contribution of TSP1/CD36 interaction to obesity-induced inflammation and IR is unknown." (PMID 37980376, 2023). "Therefore, CD36 peptide treatment may attenuate obesity/FFA induced podocyte apoptosis, reduce albuminuria and improve kidney function." (PMID 37980376, 2023). "Finally, future investigations with a large population (including obese subjects without T2D as a control group) and in different ethnic groups must be conducted to confirm these findings, and to shed light on the functional role of CD36 in obesity and on the success of diet/lifestyle interventions." (PMID 37960309, 2023). "Considering the significant role of CD36 as a receptor defining the preference for fat, taste dysfunction may be responsible for abnormalities in food intake (leading to obesity) and may not be reversed by weight loss (predisposing to a relapse)." (PMID 37960309, 2023). "However, whether this CD36 peptide can inhibit obesity-induced inflammation and IR in vivo is unknown and determined in this study in a high fat diet-induced obese mouse model (DIO)." (PMID 37980376, 2023). "In addition to directly regulating macrophage activation, other effects mediated by the TSP1/CD36 interaction may also contribute to obesity-induced inflammation." (PMID 37980376, 2023). "Moreover, CD36 interaction with GPR120 and GPR40 in taste buds is implicated in the perception of dietary lipids and may play a role in obesity-associated diseases." (PMID 35991116, 2022). "Furthermore, expression levels of CD36 and FATP4 were linked to obesity and insulin resistance." (PMID 36360622, 2022). "Therefore, the exact role of CD36 in obesity‐induced insulin resistance needs further study." (PMID 35258174, 2022). "Thus, we speculate that homeostatic alterations in CD36 and cathepsins described in obesity in adipocytes and hepatocytes could also be altered in B cells infiltrated in metabolic tissues, promoting functionals changes." (PMID 34957117, 2021). "The same pattern is obtained when we looked for the identified obesity-regulated genes: those upregulated in lean mice belong to the brown and linker genes, while highly expressed genes in obese mice were found among the white pathway genes (except cd36, which is a linker gene)." (PMID 34895148, 2021). "Muscle aging is associated with diabetes and obesity, and in the present study, we compared the expressions of the FMOD and MSTN genes and those of genes related to muscle aging (Atrogin 1, Glb1), diabetes (RAGE, CD163) and intracellular lipid accumulation (CD36, PPARγ) in vivo and in vitro." (PMID 34440852, 2021). "Therefore, it is tempting to speculate that in obesity there is an increase in the expression of CD36, which may be enhanced upon B cell activation." (PMID 34957117, 2021). "In an unforeseen finding, CD36 signaling through lysosomal impairment was shown to promote inflammasome activation in adipose tissue from obese mice, suggesting that lysosomes may be vital in obesity-induced adipose tissue inflammation." (PMID 34360006, 2021). "Hence, we can propose that CD36 and GPR120 gene methylation and/or expression could be used, in association with other known factors, as markers of obesity in children, though further research is mandatory to clarify exactly the nature of such an association." (PMID 32585828, 2020). "The hypothesis about the involvement of CD36 in the insulin resistance in adipose tissue was initiated by the observation of increased CD36 expression associated with obesity in a rodent model and humans; moreover, the analysis of transcriptional regulation of CD36 in obesity supports it." (PMID 32796572, 2020).